Y_RNA (Y RNA )
Gene: Miscellaneous RNA gene on chromosome 11 (47,726,894 to 47,726,992, reverse strand). Ensembl gene ENSG00000200090.
Homologues: Orthologues: chimpanzee Y_RNA (99% identical). Paralogues in human: RNY3 (95% identical), Y_RNA (92% identical), RNY3P1 (91% identical), Y_RNA (91% identical), Y_RNA (90% identical), Y_RNA (89% identical), Y_RNA (88% identical), RNY3P14 (87% identical), Y_RNA (87% identical), RNY3P11 (86% identical), Y_RNA (86% identical), RNY3P9 (85% identical), and 95 more.